FOSL1 (FOS like 1, AP-1 transcription factor subunit)
Diseases named in the same sentence as FOSL1 in open-access papers (continued):
Sharing a sentence is not in itself a finding about the gene and the disease.
cancer (continued). "The fact that loss-of-function experiments demonstrated that FOSL1 is important in mutant KRAS LAC argues that the overall approach integrating gene-expression and survival data is successful to identify genes with a relevant role in KRAS-driven cancer." (PMID 28220783, 2017). "Antibody specificity was validated in human cancer cells using FOSL1 shRNAs." (PMID 28220783, 2017). "Furthermore, an up-regulated inflammatory gene analysis identified the involvement of transcription factors, such as STAT4, EGR1, and FOSL1, which regulate cancer as well as inflammation in aging processes." (PMID 27153548, 2016). "These genes are involved in the regulation of cell cycle (CCND1, CDCA5, FOSL1, KDM2A, NUMA1, RHOD), apoptosis (FADD, ORAOV1), or the DNA damage response (DDB1, KAT/TIP60, MUS81, PACS1, RPS3), and several have been implicated in the HPV lifecycle and/or HPV-associated cancers." (PMID 40892869, 2025). "Interestingly, recent studies have shown that there is a complex regulatory relationship between ncRNAs and FOSL1, which can significantly influence the occurrence, development and prognosis of cancer by working together with multiple molecules and forming a complex signaling network." (PMID 40821785, 2025). "There is growing evidence suggesting that FOSL1 may contribute to drug resistance in cancer cells." (PMID 38791400, 2024). "Consequently, given the impossibility to hit a mutated allele, Cas9 and sgRNAs need to be selectively delivered to cancer cells to prevent the possible detrimental consequences of FOSL1 knockout in non-neoplastic cells." (PMID 35326630, 2022). "In addition, we dedicated a separate section of the review to the role of FOSL1 in human cancer." (PMID 35163444, 2022). "Finally, a third study described that cultured mature melanocytes could be transformed into cancer-initiating cells by overexpressing Fos-related antigen 1 (Fosl1)." (PMID 30171151, 2018). "Moreover, we posit FOSL1 as promising candidate to orchestrate the differentiation of cancer stem-like cells by repressing the 4-core genes’ expression, which severely halts cancer growth and might affect the therapeutic outcome." (PMID 30497369, 2018). "miR-19a-3p can inhibit the expression of FOSL1 at the mRNA level by binding to the 3’UTR, thus indirectly reducing the number of M2 phenotype macrophages and slowing the progression of cancer." (PMID 40821785, 2025). "FOSL1 and JUND are also significant as they have been shown to drive metastasis and invasion in various cancers." (PMID 41323280, 2025). "FOSL1 also promotes epithelial-mesenchymal transition (EMT), thereby facilitating cancer invasion and metastasis." (PMID 41423530, 2025). "Twelve DEPs were identified to be involved in pathways in cancer and three DEPs (CCND1, Fosl1, Frizzled) were related to the Wnt signaling pathway." (PMID 41184253, 2025). "In HCC cancer cells, the ectopic expression of αB-Crystallin promotes resistance to sorafenib by inducing EMT and subsequently activating the ERK1/2/FOSL1/slug signaling pathway." (PMID 38791400, 2024). "Another transcription factor, FOSL1, is also expressed by Macro_SPP1 and is known to regulate invasion and metastasis, linking with EMT and cancer cell stemness." (PMID 38521868, 2024). "To further confirm the importance of PRSS3, PAR2, and FOSL1 in promoting invasion and cancer metastasis, we overexpressed these three genes in A549‐C3 cells, which are the parental cells of A‐SSP6 cells and had low levels of PRSS3, PAR2, and FOSL1." (PMID 37395651, 2023). "Next, to examine the impacts of knocking down PRSS3, PAR2, and FOSL1 on the in vivo metastatic potential of A‐SSP6 cells, we first injected cancer cells into the tail vein of NOD/SCID mice and observed the colonies formed in the left lungs." (PMID 37395651, 2023). "The combination of four different siRNAs, targeting the gene expression of FOSL-1 and YAP, paves the way for alternative therapeutic approaches on this lethal cancer." (PMID 35804874, 2022).
cancer (continued). "FOSL1 is a member of the FOS family, playing an important role in cancer cell progression in several cell types." (PMID 36612054, 2022). "In agreement with the title of a recent review (“Targeting transcription factors in cancer-from undruggable to reality”), here we have outlined several strategies aimed at the design and delivery of FOSL1/Fra-1/AP-1-targeting molecules." (PMID 35326630, 2022). "Some genes played poor-prognostic factors in cancers, for example, ATF4 in ACC, BACH1 in LGG and UVM, and FOSL1 in DLBC and UVM." (PMID 35242279, 2022). "In ESCC cell lines, we examined all AP-1 transcription factors including JUN, FOS, MAF, and ATF family members and found that FOSL1, MAFK, BATF, and ATF5 are upregulated compared to non-cancer cells." (PMID 34722266, 2021). "Subsequently, seven common genes, including FOSL1, S100A9, CXCL12, ID2, PRS6KA3, AREG, and DUSP6, have been used as the target biomarkers for cancer diagnosis and therapy." (PMID 34490085, 2021). "Mechanistically, we find that bromodomain-containing protein 4 (BRD4) recruits Mediators and NF-κB p65 to form SEs at cancer stemness genes such as TP63, MET and FOSL1, in addition to oncogenic transcripts." (PMID 34172737, 2021). "FOSL1 (also known as FRA-1) is a member of the FOS family and has been shown to be a crucial factor in cancer cell progression and maintenance of the transformed state." (PMID 32199129, 2020). "Conversely, FOSL1 and VIM, which are ubiquitously expressed in normal mesenchymal cells and overexpressed in many cancers, had a more than 5- to 10-fold higher expression in CD44high/CD24−/low cells from triple-negative/basal-like cell lines." (PMID 32423137, 2020). "Recent data suggest a relevant role of FOSL1 in cancer motility, invasion and EMT transition in several types of human cancer." (PMID 31438567, 2019). "The validation of decreased FOSL1 (Fos-like antigen 1) and increased EMP1 was further define the potential anti-cancer effect of ZNF750." (PMID 29416636, 2018). "FOSL1, BCL2, CDK6, IL7R, RUNX2 and CDC25B have been shown to be targets of JQ1 for transcriptional silencing in other types of cancers." (PMID 27764802, 2016). "We find that the three genes that contribute the most to the formation of long feedback loops in the cancer cell line (EGR1, FOSL1, and JUNB) are all involved in the formation of the longest incomplete feedback loops observed in the non-cancer cell line." (PMID 25182846, 2014). "Both PAR2 and PAR1 activation resulted in up-regulated expression of several genes (CD44, FOSL1, TNFRSF12A, RAB3A, COPEB, CORO1C, THBS1, SDC4) known to be important in cancer." (PMID 21072196, 2010). "FOSL1 (FOS-like antigen 1), a member of the activator protein-1 (AP-1) transcription factor family, has emerged as a critical mediator at the intersection of inflammation, epithelial homeostasis, and cancer progression." (PMID 42193998, 2026). "Finally, our group has recently identified a subset of PARP7‐dependent cancer cells that are driven by the AP1 transcription factor and oncogene FRA1 (FOSL1)." (PMID 39502005, 2025). "Despite extensive endeavors, no drugs targeting AP-1 or FOSL1 for cancer treatment have been approved for clinical use." (PMID 38791400, 2024). "The scRNA-seq data from four different cancer cell lines (A549, DU145, MCF7, and OVCA420) revealed that signaling pathways known to drive EMT- like TGFβ1, EGF, and TNF- converge on NF-κB and FOSL1, before initiating the expression of typical EMT master regulators such as STAIL, TWIST, and ZEB." (PMID 38856747, 2024). "Notably, among the genes downregulated upon DSCAM-AS1 knockdown were several proliferation activators of endometrial (and other) cancer cells, like NOTCH1, HMGA2, PTK2/FAK, FOSL1, GREM1 and EGR1." (PMID 35885035, 2022).
cancer (continued). "While no clinical trial based on FOSL1 silencing has been registered so far, cancer patients have been experimentally treated with the miR-34a oncosuppressor, which targets the FOSL1 mRNA." (PMID 35326630, 2022). "Thus, the experimental data suggest that FOSL1 induces the genes required for EMT and the following migration and invasion of the cancer cells." (PMID 35163444, 2022). "However, genes associated with cell differentiation (EPCAM, CK8, CK18, and FOXA2), EMT (SNAI1, FOSL1, and ID1), and cancer stem cells (CD44, CD133, ETV1, MALAT1, NEAT1, and NESTIN) displayed a more varied response compared to 2D cells." (PMID 33356003, 2021). "In contrast, among potential target genes of miR-34a, miR-424, and miR-503, vascular endothelial growth factor A (VEGFA) and FOS-like 1 (FOSL1) expression did not exhibit clear correlations with poor prognosis in patients with basal-like cancer." (PMID 29872500, 2018). "Consistent with expectations, canonical luminal genes such as ESR1, GATA3, FOXA1, TFF1 and IGF1R were higher in ER+ samples compared to triple negative samples, while proliferation and mesenchymal genes such as SPRY2, SNAI2, FOSL1, MET and BUB1 were higher in triple negative cancers." (PMID 24520381, 2014). "Interestingly, when we elevated the levels of FOSL1 and JUN simultaneously, the lung metastatic ability of cancer cells did not increase compared with cells that only had FOSL1 overexpression." (PMID 37395651, 2023). "Indeed, in our LAC models of acquired JQ1 resistance, we did not see reactivation of the anti-cancer target of BETi in this cancer type, FOSL1." (PMID 33712563, 2021). "Functions of the remaining genes - including CSNK1E, FOSL1, PPP2R1A, and PPARD – are widely reported as being relevant to cancer (if not specifically NSCLC) biology." (PMID 33027769, 2020). "On the other hand, JUN, JUND, and FOSL1, another set of potential targets of HSF1 upregulated after heat shock, were expressed at higher levels (or not significantly changed) in all analyzed HSF1high cancers." (PMID 36010586, 2022).
infection (13 papers, 2013 to 2025). The state of being infected such as from the introduction of a foreign agent such as serum, vaccine, antigenic substance or organism. "Among the most significant differentially expressed genes, we noticed a downregulation of genes associated with cell death during infection, including FosL1, Mt-Co3, and Mt-Co1, among others." (PMID 35984745, 2022). "CCK-8 assay showed that overexpressed FOSL1 in EPHB2 siRNA-transfected Schwann cells by lentivirus infection slightly increased the optical density values of Schwann cells from about 83.82% of the control group to about 90.77%." (PMID 37949219, 2023). "The expression of FOSL1 was also increased in immune cells (THP-1 and peritoneal macrophages [pMs]) after infection with VSV." (PMID 28049150, 2017). "Under Ad-vaspin infection, we observed increases in the levels of c-Fos and c-Jun but no changes in Fosl1, Fosl2, FosB, JunB or JunD." (PMID 40025171, 2025). "The discovery of FOSL1 inhibition of IFN-I responses by interfering with ubiquitination of TRIF and TRAF3 and the interaction of the two molecules with TBK1 could potentially be explored for developing strategies to modulate host IFN-I responses to infections." (PMID 28049150, 2017).
cardiovascular disease (3 papers, 2021 to 2023). "One study revealed that FOSL1 can directly activate P21 and P16 signaling to promote vascular senescence, and vascular aging is one of the principal risk factors owing to the high mortality of cardiovascular disease." (PMID 36831172, 2023).
metabolic disorders (1 paper, 2022). "In this study, we found that CXXC5 was specifically induced with suppressing Wnt/β-catenin pathway target genes such as GLP1, TCF7L2, WISP1, and fos-related antigen 1 (FOSL1) in the liver tissues of NASH patients with metabolic disorders." (PMID 36114279, 2022).
FOSL1 also shares sentences with these, for which no sentence is quoted: hepatocellular carcinoma (10 papers); thyroid cancer (8); rheumatoid arthritis (6); esophageal squamous cell carcinoma (5); oral squamous cell carcinoma (5); astrocytoma (4); ductal carcinoma in situ (4); benign tumors (3); breast invasive ductal carcinoma (3); diabetes (3); ductal breast carcinoma (3); Fibroadenoma (3); interstitial lung disease (3); invasive carcinoma (3); neuroblastoma (3); penile squamous cell carcinoma (3); adenocarcinoma (2); autoimmune disorders (2); breast (2); breast adenocarcinoma (2); breast diseases (2); colon adenocarcinoma (2); fibrosarcoma (2); inflammatory bowel disease (2); lipid metabolism disorder (2); lung squamous cell carcinoma (2); malignant mesothelioma (2); metastatic cancers (2); non-small cell lung carcinoma (2); oral cancer (2).
A further 69 diseases each share a sentence with FOSL1 in 2 papers or fewer.